CD24 (CD24 molecule)
Diseases named in the same sentence as CD24 in open-access papers (continued):
Sharing a sentence is not in itself a finding about the gene and the disease.
colorectal cancer (continued). "The distribution of CD44+/CD24+ cells in colorectal cancer is under dispute, although it has been demonstrated that between 50 and 68% of patients suffering from colorectal cancers have high level of CD24+ cells." (PMID 28030837, 2017). "CD24 upregulation has been shown during the progression of colorectal cancer and has been considered a potential target for early intervention in the prevention and treatment of colorectal cancer." (PMID 28611669, 2017). "Recent studies demonstrated that CD44+/CD24+ colorectal cancer cells show greater clonogenic potential in vitro and tumor initiation in vivo." (PMID 28030837, 2017). "Our previous study confirmed that CD24 was involved in the metastasis of colorectal cancer through MAPK signal pathway." (PMID 27494878, 2016). "(Please cite as: NosratiA, NaghshvarF, Maleki I,Salehi F. Cancer stem cells CD133 and CD24 in colorectal cancers in Northern Iran." (PMID 27099673, 2016). "Our results showed that CD24 expression was closely related to MVD in primary colorectal cancer tissue and liver metastasis tissue." (PMID 27494878, 2016). "LYN promotes colorectal cancer development via CD24-mediated ERK1/2 activation, and dasatinib is effective in treating metastatic prostate cancers harboring activated LYN." (PMID 27756880, 2016). "In human colorectal cancer, CD24 expression is significantly correlated to late tumor stages and lymph node metastasis." (PMID 27659530, 2016). "Collectively, we concluded that CD24 was involved in colorectal cancer angiogenesis in Hsp90-dependent manner." (PMID 27494878, 2016). "In this study, cell surface markers CD44 and CD24 were thus used to select CCSCs from human colorectal cancer cell lines." (PMID 24696849, 2014). "It has been reported that cytoplasmic CD24 expression in colorectal cancer is independently correlated with the shortened patient survival." (PMID 24696849, 2014). "CD133, CD44 and CD24 are three proposed stem cell markers in colorectal cancer, but discouragingly the distribution differs between patients and tumor cell lines." (PMID 24760019, 2014). "Apart from CD44 expression, CD24+ cells are also reported to act as cancer stem cells in ovarian and colorectal cancers." (PMID 22693526, 2012). "Our previous data indicated that CD24 promoted the proliferation and invasion of colorectal cancer cells through the activation of ERK1/2." (PMID 22731636, 2012). "Similarly, in colorectal cancer, abnormally strong cytoplasmic CD24 expression was seen in 24% of cases and was significantly associated with shortened distant metastasis-free survival." (PMID 40486886, 2025). "SWA11, a newly developed anti‐CD24 mAb, significantly blocked tumor growth of colorectal cancer." (PMID 41346572, 2025). "Also, in colorectal cancer and non-small cell lung cancer (NSCLCs), the cytoplasmic expression of CD24 has been identified as an independent prognostic marker for patient survival." (PMID 39687458, 2024). "CD24 has been found in 90% of adenoma and 86% of malignant lesions, which suggests that the change in the expression of CD24 is involved in the occurrence and development of colorectal cancer (CRC)." (PMID 37919766, 2023). "Protein extracted from PBLs was subjected to immunoblotting using anti-CD24 monoclonal antibodies, showing that the sensitivity and specificity of CD24 for distinguishing colorectal cancer from normal subjects were 70.5% (95% CI, 54.8–83.2%) and 83.8% (95% CI, 74.6–92.7%), respectively." (PMID 38138858, 2023). "Furthermore, treatment with anti-CD24 antibodies conferred increased sensitivity to multiple chemotherapy agents in colorectal cancer models." (PMID 36013184, 2022).
colorectal cancer (continued). "As a putative tumour-propagating cell marker, elevated CD24 expression has been documented in lung, breast, ovarian and brain cancers, and has been affiliated with high Shh/Ptch1 pathway activity in both colorectal cancer and medulloblastoma formation." (PMID 30657775, 2019). "To validate the effects of JIB-04 on the mRNA expression of β-catenin target genes, we measured the mRNA levels of CSC-associated genes (CD44, LGR5, DKK1, ALDH1A3, ALDH1B1, CD24, and SOX4) by qRT-PCR in three different colorectal cancer cell lines after treament with JIB-04." (PMID 29700375, 2018). "The results showed that the tumorigenic capacity was significantly reduced, the sphere-forming efficiency was decreased and the ratio of CD44+CD24+ cells and the number of colospheres were also obviously reduced in colorectal cancer cells after overexpression of RORβ." (PMID 28137278, 2017). "Furthermore, CD24 also was regarded as a poor prognosis marker in various cancer patients, such as breast cancer and colorectal cancer(CRC)." (PMID 27494878, 2016). "CD24 is involved in tumor progression of various cancers, but the effects of CD24 on tumor angiogenesis in colorectal cancer are still unknown." (PMID 27494878, 2016). "CD24 overexpression was correlated to decreased survival in colorectal cancer." (PMID 26394139, 2015). "However, recent studies on colorectal cancer cell lines demonstrated that CD44+/CD24+ cells showed greater clonogenic ability in vitro and tumour initiation in vivo." (PMID 22693526, 2012). "In addition, our findings demonstrate that knockout of TRIM28 in Caco2 colorectal cancer cells is associated with a pronounced upregulation of immune checkpoint molecules CD47 and CD24 on both mRNA and protein levels, particularly in clones exhibiting concurrent downregulation of CD133." (PMID 41303350, 2025). "Anti-CD24 monoclonal antibodies have also been conjugated with Pseudomonas-derived exotoxin; this approach produced dose-dependent cytotoxicity in CD24-expressing colorectal cancer cells and inhibited tumor growth in xenograft models, with the results replicated in a second preclinical study." (PMID 36013184, 2022). "Using Random Survival Forest (RSF) analysis with importance scoring, we identified seven key prognostic genes (CD24, SLC25A5, HSPB1, CD9, SPIMK1, LGALS4, and CEACAM5), which were subsequently designated as the Colorectal cancer Survival Signature (CSS)." (PMID 40777020, 2025). "In colorectal cancer, the ALDH proteins, especially ALDH1A1and ALDH1A3, contribute to the chemoresistance as well as increased CSC markers such as CD133, CD166, CD24, CXCR4, CD26, CD271, and CD274." (PMID 41346572, 2025). "The study demonstrated that the ERK1⁄2 pathway was activated in colorectal cancer (CRC) and the MEK1⁄2 inhibitor abrogated CD24-induced proliferation." (PMID 37919766, 2023). "The results revealed LAG3, CD24-SIGLEC10 and HBEGF-CD9 pathways as potential therapeutic targets for dual mutant colorectal cancers." (PMID 36172359, 2022). "Colorectal cancer stem cells express several cell surface markers, such as CD44, CD24, CD133 and CD146." (PMID 29642386, 2018). "We aimed to study the expression of CD24 and CD133 in colorectal cancer and normal adjacent tissues to assess a relationship between these markers and clinic-pathological characteristics and patient’s survival." (PMID 27099673, 2016). "The combined biomarkers CD44 and CD24 have been identified as CSC surface markers in breast, prostate, pancreatic, and colorectal cancers." (PMID 27521216, 2016). "Expression of CD24 and CD133 was studied in a paraffin block of colorectal cancer and normal tissues near tumors with the immuneohistochemical method in patients who were referred to Imam Khomeini Hospital in Sari." (PMID 27099673, 2016). "Many reports have shown that CD24 expresses not only in the membrane but also in the cytoplasm in PDAC and colorectal cancer." (PMID 27332878, 2016).
colorectal cancer (continued). "We next isolated CCSCs from human colorectal cancer cell lines, including SW480 cells, LOVO cells, and HCT116 cells by MACS using antibodies against CD44 and CD24." (PMID 24696849, 2014). "Several colorectal cancer CSC markers have been reported to date, including CD133, CD44, CD24, CD166, and Lgr-5." (PMID 25396735, 2014). "Both CD24 and CD44 have been reported as putative markers for isolating colorectal cancer—initiating cells or CCSCs." (PMID 24696849, 2014). "To investigate further the signalling pathways addressed by CD24 and their possible implications for cancer progression, we first investigated whether ectopic expression of CD24 is able to increase the activity of Src and its downstream signalling axis in a panel of colorectal cancer cell lines." (PMID 23533633, 2013). "In colorectal cancer, CD133+/CD24+ cells exhibit great clonogenic potential and multilineage differentiation, the expression of CD133 and CD24 also correlates with the expression of EGFR, KRAS, Ki67 as well as stemness‐related signaling pathways such as Wnt/β‐catenin and Hedgehog signaling pathways." (PMID 41346572, 2025). "CD44, CD24, and ALDH1 are hypothesized to be specific markers for the identification, isolation, and monitoring of human colon CSCs during colorectal cancer development." (PMID 38787133, 2024). "Additionally, high expression of CD44, CD24, and ALDH1 have been identified as specific markers for identifying, isolating, and tracking human colonic CSCs during the development of colorectal cancer." (PMID 38787133, 2024). "Briefly, Rg3 repressed the cancer stemness in both colorectal cancer (LoVo, SW620, HCT116) and liver cancer cells (HepG2, MHCC-97L) via reductions in CD24, CD44, and the epithelial cell adhesion molecule (EpCAM) and activation of ARHGAP9, a tumor suppressor gene." (PMID 36012338, 2022). "In colorectal cancer cells, CUR decreased the expression of CD24 in a dose-dependent manner." (PMID 33800000, 2021). "In colorectal cancer cells, CUR may exhibit its action against metastasis by downregulating CD24, FAK, and Sp-1, and upregulating the expression of E-cadherin." (PMID 33800000, 2021). "In addition, MG cells expressed surface markers of colorectal cancer stem cells (ALDH1A1, CD24, POU5F1, SOX2, and SOX9) to a greater degree compared with non-MG cells." (PMID 31936744, 2020). "For example, in one study strong c-CD24 expression was correlated with shortened survival in colorectal cancer patients even without distant metastases." (PMID 28052035, 2017). "Interestingly, CD24 is known to enhance cell migration and proliferation via regulation of signaling molecules like Cten, FAK and ERK1/2 in colorectal cancer." (PMID 26608463, 2015). "Nodal transcript and protein were hardly detectable in CD44- or CD24-negative human colorectal cancer cell lines, whereas Nodal and its receptors were present in CCSCs." (PMID 24696849, 2014). "In a previous immunohistochemical study on colorectal cancer from the several potential CSC markers (ABCG5, ALDH1, CD24, CD44, CD90, CD133, EpCam) that have been proposed for solid tumors, only ABCG5 expression in tumor budding cell was found to be associated with poor survival of the patients." (PMID 23316479, 2012). "To verify that NRIP2 is expressed at a higher level in CCICs, we isolated CD44+CD24+ colorectal cancer-initiating cells from primary colorectal P1 and SW620 cells by fluorescence-activated cell sorting (FACS) and colospheres from colorectal cancer cell lines and primary colorectal cancer tissues." (PMID 28137278, 2017). "Up-regulation of CD24 expression has documented negative prognostic impact in patients with cancers as diverse as ovarian, breast, prostate, hepatocellular, non-small cell lung, colorectal cancer and gastric adenocarcinoma." (PMID 23166783, 2012).
colorectal cancer (continued). "Studies indicate that up-regulation of CD24 might be a feasible mechanism of resistance in colorectal cancer CRC, improving CRC cells' sensitivity to oxaliplatin (L-OHP)-induced cytotoxicity by GRP78 suppression, is closely correlated with down-regulation of CD24." (PMID 33514437, 2021). "As AMBRA1 affected CTNNB1 transcription via ALDH1B1, which is a crucial CSC marker of colorectal cancer, we next investigated whether AMBRA1 expression affects the mRNA levels of several CSC-related β-catenin target genes, including LGR5, HIF1a, ALDH1A3, CD24, and SOX4." (PMID 34769507, 2021). "SIX is enriched in the CD44+CD24-/low subpopulation, whereas DACH might act as a tumor suppressor to reduce the number of BCSC subpopulations in vitro and in vivo though phosphorylating GSK3β and inhibiting Wnt signaling, compliance with findings in colorectal carcinomas." (PMID 27793013, 2017). "However, CD44+/CD24+ cells, not CD44+/CD24− cells, harbor CSC capacity in pancreatic and colorectal cancers." (PMID 27521216, 2016).
hepatocellular carcinoma (61 papers, 2003 to 2026). A malignant tumor that arises from hepatocytes. "Significantly, targeted mutation of CD24 has been shown to reduce the size of hepatocellular carcinomas induced by the transgenic expression of hepatitis virus B genes." (PMID 38881902, 2024). "The CD24/Siglec-10 interaction has been linked with NK cell dysfunction in hepatocellular carcinoma and could provide another pathway for CD24-mediated immune evasion." (PMID 36013184, 2022). "CD24 has been identified as a biomarker for neural lineage differentiation of human stem cells and been shown to directly affect the risk and progression of hepatitis B virus, demonstrating increased risk of more rapid progression to liver cirrhosis and hepatocellular carcinoma." (PMID 30044847, 2018). "MICA was attached to rG7S, a single-chain antibody fragment (scFv) targeting the tumor-associated antigen CD24 to form a fusion protein rG7S-MICA to treat hepatocellular carcinoma (HCC)." (PMID 28036020, 2016). "CD24 is a small, heavily glycosylated mucin-like cell surface protein anchored to the membrane by phosphatidylinositol and has been shown to be overexpressed in stem/progenitor cells and has been linked to CSCs derived from breast, colon, ovarian, pancreatic, and hepatocellular carcinomas." (PMID 27610139, 2016). "In hepatocellular carcinoma, overexpression of CD24 leads to increased production of PP2A protein, induces inactivation of the AKT/mTOR pathway, elevates autophagy levels, and results in resistance to sorafenib." (PMID 40486886, 2025). "The Hippo-YAP pathway has also been shown to indirectly regulate CD24 expression through the transcription factor SOX4 in hepatocellular carcinoma and promote tumor progression." (PMID 40486886, 2025). "This high expression of CD24 also promotes the development of chemoresistance in hepatocellular carcinoma." (PMID 40486886, 2025). "Similar findings were confirmed in hepatocellular carcinoma, with CD24 protein demonstrating cytoplasmic immunostaining in HCC tumour cells and negative expression in neighbouring non-tumorigenic liver tissue." (PMID 38137380, 2023). "Further, in preclinical models of hepatocellular carcinoma, anti-CD24 ADCs including CD24 antibody-conjugated doxorubicin G7mAb-DOX and the hG7-BM3-VcMMAE conjugates showed antitumor activities in vivo." (PMID 36910604, 2023). "An investigation has been reported that took into consideration the cluster of differentiation 24 (CD24) which is overexpressed in many solid tumors, such as hepatocellular carcinoma, and rarely expressed in normal cells." (PMID 36077778, 2022). "This approach employed the increased expression of CD24 in hepatocellular carcinoma tumor cells in order to recruit NK cells at the tumor site and promote NK cell-mediated cytotoxicity, consequently showing substantial antitumor activity in vivo." (PMID 36013184, 2022). "A conjugate bearing doxorubicin induced cell cycle arrest in CD24+ hepatocellular carcinoma cells and impeded tumor growth in mice." (PMID 36013184, 2022). "For example, one study designed a NO-releasing antibody against CD24+, a widely expressed hepatocellular cancer marker, and was found to have high cellular uptake and apoptotic activity." (PMID 33513777, 2021). "For example, MALAT1 functioned as a competing endogenous RNA (ceRNA) by sponging miR-3064-5p, which alleviated the suppressive effect on angiogenesis in human hepatocellular carcinoma via the FOXA1/CD24/Src pathway." (PMID 34012919, 2021).